PRELID3A (PRELI domain containing 3A)
Description:
In vitro, the TRIAP1:PRELID3A complex mediates the transfer of phosphatidic acid (PA) between liposomes and probably functions as a PA transporter across the mitochondrion intermembrane space. Phosphatidic acid import is required for cardiolipin (CL) synthesis in the mitochondrial inner membrane.
Synonyms: C18orf43; SLMO1; HFL-EDDG1; FLJ31484
Tractability: PROTAC: its protein half-life has been measured.
Gene: Protein-coding gene on chromosome 18 (12,407,896 to 12,432,238, forward strand). Ensembl gene ENSG00000141391.
Subcellular location: Mitochondrion
Gene Ontology:
Molecular function: phosphatidic acid transfer activity; protein binding
Biological process: phospholipid transport
Cellular component: mitochondrion; mitochondrial intermembrane space
Genetic constraint (gnomAD): Loss-of-function variants: 19 observed, 15.03 expected, observed/expected ratio (o/e) 1.26, 90% interval 0.88 to 1.79. The upper end of that interval is the gene's LOEUF score, 1.79, which puts it in group 6 of 6, group 1 being the genes least tolerant of losing a copy. Missense variants: 188 observed, 182.66 expected, observed/expected ratio (o/e) 1.03, 90% interval 0.91 to 1.16. Synonymous variants: 77 observed, 70.14 expected, observed/expected ratio (o/e) 1.1, 90% interval 0.91 to 1.33.
Homologues: Orthologues: chimpanzee PRELID3A (94% identical), macaque PRELID3A (94% identical), mouse Prelid3a (90% identical), rat Prelid3a (90% identical), guinea pig PRELID3A (89% identical), rabbit PRELID3A (86% identical), dog PRELID3A (84% identical), pig PRELID3A (83% identical), zebrafish prelid3a (77% identical), tropical clawed frog prelid3a (60% identical), Drosophila melanogaster slmo (49% identical), Caenorhabditis elegans F15D3.6 (38% identical). Paralogues in human: PRELID3B (71% identical), PRELID1 (27% identical), PRELID2 (26% identical).
Diseases named in the same sentence as PRELID3A in open-access papers:
PRELID3A is named in the same sentence as 2 diseases in open-access papers, as found by Europe PMC text mining. Sharing a sentence is not in itself a finding about the gene and the disease.
PRELID3A shares sentences with these, for which no sentence is quoted: breast tumors (1 paper); colorectal cancer (1).